DIRC3 (disrupted in renal carcinoma 3)
Diseases named in the same sentence as DIRC3 in open-access papers (continued):
Sharing a sentence is not in itself a finding about the gene and the disease.
meningioma (2 papers, 2023 to 2026). A generally slow growing tumor attached to the dura mater. "It was also demonstrated that tandem duplication of a super‐enhancer overlapping DIRC3 and Hedgehog ligand IHH leads to formation of novel interactions between the promoter of IHH and the DIRC3 enhancer in meningioma." (PMID 39853740, 2026).
breast tumour (1 paper, 2021). "Since IGFBP5 is a physiological regulator of epithelial cell survival in the mammary gland, it was proposed that a deregulation of IGFBP5 expression induced by variants located upstream of DIRC3 could lead to the development of a breast tumour." (PMID 33747362, 2021).
familial renal carcinoma (1 paper, 2021). "DIRC3, first identified as a fusion transcript in familial renal carcinoma as early as 2003, was identified to affect thyroid-stimulating hormone levels and promote TC development through decreasing thyroid epithelium differentiation." (PMID 34950210, 2021).
gastric cancer (1 paper, 2022). A primary or metastatic malignant neoplasm involving the stomach. "The results of our study demonstrated that the five-lncRNAs PART1, UCA1, DIRC3, HOTAIR, and HOXA11AS require more investigation to be confirmed as diagnostic biomarkers in gastric cancer." (PMID 35949302, 2022).
periodontitis (1 paper, 2022). An acute or chronic inflammatory process that affects the tissues that surround and support the teeth. "A number of other long non-coding RNAs, namely Linc0116, Linc00667, CDK6-AS1, FENDRR and DIRC3 have been found to be down-regulated in the blood samples of patients with periodontitis." (PMID 36456933, 2022).
renal carcinoma (1 paper, 2021). A carcinoma arising from the epithelium of the renal parenchyma or the renal pelvis. "Both are located within introns of DIRC3 (which stands for disrupted in renal carcinoma gene 3), a long non-coding RNA gene characterized by its role in renal carcinoma (data not shown)." (PMID 34832643, 2021).
skin cancer (1 paper, 2022). "It has been shown that DIRC3 can be used to identify novel targets for skin cancer treatment." (PMID 36581632, 2022).
thyroid tumour (1 paper, 2021). "These two SNPs were highly correlated to rs57481445 (r2 > 0.9) and also strongly associated with the expression of DIRC3 and IGFBP5 (insulin growth factor binding protein 5) in thyroid tumour cells, according to TCGA data." (PMID 33747362, 2021). "This SNP was strongly associated with the expression of the two nearby genes DIRC3 and IGFBP5 in thyroid tumour cells, according to TCGA data." (PMID 33747362, 2021). "It is also associated with expression of DIRC3 and of the nearby gene IGFBP5 in thyroid tumour cells." (PMID 33747362, 2021).
tumor (17 papers, 2016 to 2025). "DIRC3 codifies a lncRNA that was first associated with renal cancer, suggesting a tumor suppressor role." (PMID 33218058, 2020). "IGFBP5 reduction produces comparable results, confirming that DIRC3 mediates tumour suppression via IGFBP5 activation." (PMID 41463281, 2025). "Mechanistically, DIRC3 seems to promote expression of the tumor suppressor IGFBP5 through a chromatin loop, which brings both genes into close proximity." (PMID 33329688, 2020). "DIRC3 and IGFBP5 (insulin-like growth factor binding protein 5) tumor suppressors are within the same topologically associated domain." (PMID 33218058, 2020). "Although the function of DIRC3 is unknown, it is thought to have tumor suppressor activity." (PMID 32059462, 2020). "Specifically, this network suppresses DIRC3 transcription, which in turn regulates chromatin accessibility to limit SOX10 and maintain expression of tumour-suppressive genes such as IGFBP5." (PMID 41463281, 2025). "Our bioinformatics data illustrated that lncRNAs PART1, UCA1, DIRC3, HOTAIR, and HOXA11AS have more differential expression in the tumor tissues versus normal counterpart margins." (PMID 35949302, 2022). "Disrupted in Renal Carcinoma 3 (DIRC3) lncRNA is, instead, a MITF-SOX10-regulated nuclear lncRNA, exerting its tumor-suppressor function by cis-acting and, in particular, by chromatin remodeling." (PMID 33503876, 2021). "DIRC3 therefore appears to act through IGFBP5 to regulate growth in soft agar and exert its tumour suppressor effect." (PMID 31881017, 2019). "We found significant cis-eQTL of genes near NRG1, NKX2-1, DIRC3, PCNXL2 and VAV3 in the normal and tumour thyroid tissue." (PMID 28703219, 2017). "DIRC3 acts in the nucleus and has been shown to activate expression of the neighbouring insulin-like growth factor binding protein 5 (IGFBP5) gene, which shapes tumour suppression by modulating the insulin-like growth factor 1 receptor (IGF1R) pathway." (PMID 41463281, 2025). "DIRC3 is a nuclear tumor suppressor lncRNA that activates the expression of IGFBP5 by modulating chromatin structure and preventing SOX10 binding to the regulatory elements of the DIRC3 locus." (PMID 40002172, 2025). "Our work suggests that one of these, Disrupted In Renal Carcinoma 3 (DIRC3), may be a clinically important MITF-SOX10 regulated tumour suppressor." (PMID 31881017, 2019).
cancer (4 papers, 2017 to 2023). A tumor composed of atypical neoplastic, often pleomorphic cells that invade other tissues. "In turn, DIRC3 dependent regulation of IGFBP5 impacts the expression of genes involved in cancer associated processes and is needed for DIRC3 control of anchorage-independent growth." (PMID 31881017, 2019). "This is similar to the effect of DIRC3 depletion and is consistent with our transcriptomic experiments showing that DIRC3 activates IGFBP5 to control shared gene expression programmes involved in cancer." (PMID 31881017, 2019). "We found several cellular growths or cancer-related pathways that were associated with SNPs of NRG1, VAV3, DIRC3, SEPT11 and INSR." (PMID 28703219, 2017). "DIRC3 and RMST both were associated with the “Pathways in cancer” and “Endocytosis”." (PMID 35356464, 2022). "Our results reveal that DIRC3 activates expression of the neighbouring Insulin Like Growth Factor Binding Protein 5 (IGFBP5) tumour suppressor gene to control gene expression programmes involved in cancer." (PMID 31881017, 2019). "Moreover, we also discovered that DIRC3 and IGFBP5 common target genes are enriched for regulators of cancer associated processes such as cell migration, proliferation, metabolism and mesenchymal cell differentiation." (PMID 31881017, 2019). "We also discovered that DIRC3 functions as a new transcriptional regulator to activate its neighbouring IGFBP5 gene and control genome-wide expression programmes involved in cancer." (PMID 31881017, 2019).
DIRC3 also shares sentences with these, for which no sentence is quoted: laryngeal squamous cell carcinoma (3 papers); metastatic melanoma (2); renal cell carcinoma (2); Alzheimer disease (1); colorectal cancer (1); endometrial cancer (1); ovarian carcinoma (1); prostate carcinoma (1); thyroid (1).